PTGS2 (prostaglandin-endoperoxide synthase 2)
Diseases named in the same sentence as PTGS2 in open-access papers (continued):
Sharing a sentence is not in itself a finding about the gene and the disease.
tumor (continued). "PTGS2 (COX-2) might shift its primary pro-tumor role to promote a potent immune response, thereby acquiring an anti-tumor effect." (PMID 37762335, 2023). "Interestingly, Ptgs2 was highly elevated in tumor tissues of the low tumor group (GM:LEW) at 6 months of age." (PMID 37458451, 2023). "We further evaluated the mRNA expression of PTGS2, a marker for assessment of ferroptosis in vivo, finding that U104 combined with cisplatin significantly increased the PTGS2 expression in isolated tumor tissues." (PMID 36760347, 2023). "Recent studies pointed out that the mesenchymal niche manipulated the initiation of colorectal cancer by the rare peri-cryptal Ptgs2-expressing fibroblasts, and these fibroblasts exhibited paracrine control over tumor-initiating stem cells via the PGE2-EP4-Yap signaling axis." (PMID 36765694, 2023). "NR2C2, MAPK8, PPARA, and PTGS2 are all downregulated in tumor versus normal tissues." (PMID 35814450, 2022). "PTGS2 is a cyclooxygenase involved in pain, inflammation, and tumor formation." (PMID 35855823, 2022). "We found that the PTGS2 showed higher expression in tumor tissues." (PMID 36555343, 2022). "What’s more, prostaglandin E2, the product of PTGS2, was reported to stimulate tumor progression." (PMID 35910372, 2022). "The newly transcribed LncRNA PACERR interacts directly with CTCF, forming the CTCF/PACERR complex to recruit HAT EP300, resulting in increased chromatin accessibility and transcriptional activation of PTGS2, the critical driver of M2 polarization and pro‐tumour functions in TAMs." (PMID 35184402, 2022). "PTGS2 is closely related to apoptosis and promotes tumor progression." (PMID 35237519, 2022). "Finally, this study demonstrates that PAM inhibits tumor growth in a xenograft model with an increase in 4-hydroxynoneal and PTGS2, a byproduct of lipid peroxidation, and a decrease in FSP1 expression." (PMID 35256587, 2022). "PTGS2 and PGE2 could promote cancer progression by affecting the differentiation and survival of tumor-associated immune cells, and shifting the tumor microenvironment into an immunosuppressive environment." (PMID 35411258, 2022). "In addition, for some tumors, tumor-derived PTGS2 serves an essential role in tumor immune evasion by inducing PGE2 to successfully evade elimination induced by type I interferon and/or T cells." (PMID 36097539, 2022). "The TLR4 activation, the receptor for LPS generated by the gut microbiome in the epithelial cells, can induce tumor development by up-regulating prostaglandin-endoperoxide synthase 2 (PTGS2) and activating the epidermal growth factor receptor (EGFR) signaling pathway in mice receiving AOM." (PMID 34556055, 2021). "Furthermore, the gene expression alterations in tumour tissues were consistent with the in vitro observations: upregulation of PTGS2 and CYP2E1 and down-regulation of TP63 and KRT5." (PMID 33359448, 2021). "We compared the mRNA expression levels of Ptgs2 and effector genes in the samples obtained from tumor-bearing or healthy mice, namely, tumor or healthy colon, Ficoll purified buffy coat, and Parsortix-isolated cells to find different patterns between healthy, tumor-bearing mice with or without CTCs." (PMID 35153760, 2021). "Retinoids have prevented the induction of PTGS2 by mitogenesis and tumour promoter, thus this indicates that dysregulation of normal retinoid response may fail to downregulate PTGS2." (PMID 33995625, 2021). "Moreover, silencing PTGS2 in Skov3-ip1 cells in vivo completely abrogated stress-mediated changes in tumor growth and metastasis." (PMID 33114769, 2020). "Consistent with our expectations, peri-necrotic tumor cells exhibited increased PTGS2 expression." (PMID 33110073, 2020). "Neither gPTGS2 total levels quantified in tissue lysates nor tumor-associated PTGS2 scored by IHC influenced patients OS in our cohort." (PMID 32168749, 2020). "The influence of tumor PTGS2 expression on CRC patient prognosis is difficult to interpret." (PMID 32168749, 2020).
tumor (continued). "We suggest that stromal PTGS2 could exert a positive effect on patients OS when expressed in the luminal area of the tumor." (PMID 32168749, 2020). "In the Skov3-ip1 and HeyA8 orthotopic models of ovarian cancer, they showed that the blockade of adrenergic signaling with the non-selective β-blocker propranolol or the β2-adrenergic receptor specific blocker terbutaline decreased levels of PTGS2 in tumor cells." (PMID 33114769, 2020). "These analyses, comparing tumor and normal colon epithelia, showed that gene expressions from several members of this pathway are upregulated in tumors, namely PTGS2, PTGES, and TBXAS1, indicating that the biosynthetic and signaling pathways of PGE2 and TXA2 are favored in established tumors." (PMID 32410997, 2020). "High-level tumor miR-21 expression may potentiate the PTGS2/PGE2 pathway and suppress antitumor immunity." (PMID 31539405, 2019). "Lastly, PTGS2 was proved to facilitate tumor cell proliferation and improve the radio‐tolerance." (PMID 30740906, 2019). "Importantly, we discovered that MDMX correlates with the increased transcription of CXCR4 and PTGS2 in tumor tissue." (PMID 30642351, 2019). "Furthermore, the reduction of COX2, a product of gene PTGS2, was confirmed with immunohistochemical staining in both xenograft tumor tissue sections." (PMID 31489113, 2019). "This study further reveals that gastric acid stress-induced acceleration of tumor formation from mutant foregut basal progenitors is dependent on epithelial-specific prostaglandin-endoperoxide synthase 2 (Ptgs2, also known as cyclooxygenase-2, Cox-2) expression." (PMID 31110179, 2019). "We found that components of the antigen processing pathway (H2-K1, β2 m) were elevated in A9 metastatic tumours expressing IL-33, whereas the expression of immunosuppressive factors (IL-10, Ptgs2) were diminished, thereby altering the tumour microenvironment toward immune responsiveness." (PMID 29440650, 2018). "In addition to increased density, cDC1 often formed multicellular clusters within Ptgs1/Ptgs2−/− BRAFV600E tumor tissue." (PMID 29429633, 2018). "Moreover these tumours displayed elevated expression of PTGS2 compared with tumours arising from WT Ishikawa cells." (PMID 21589857, 2011). "The activation of IGF1, BCL2 and CCND1 by PTGS2 might be the prolonged legacy of chronic inflammation in early stages of tumor generation." (PMID 17206280, 2007). "In addition, we found that tumor related genes, such as PTGS2, ADAM17 and FOS, are highly expressed in the ITA infection group, suggesting that ITA may lead to more severe N. farcinica infections." (PMID 40723822, 2025). "Additionally, studies show that quercetin and beta-sitosterol reduce cancer-related inflammation and tumor growth by inhibiting the expression and activity of PTGS2, supporting the relevance of our docking results where quercetin binds to PTGS2." (PMID 39712495, 2024). "Similarly, leptin knockout in obesity-derived adipocytes reduced tumor growth of triple negative breast cancer (BT20) which was associated with reduced expression of angiogenesis-promoting genes (e.g., SERPINE1, SNAI2, IL-6, TWIST1, and PTGS2)." (PMID 39439572, 2024). "Moreover, other ferroptosis marker genes were differentially affected by erastin and IKE in tumor tissues; specifically, prostaglandin-endoperoxide synthase 2 (PTSG2) was significantly increased, whereas glutathione peroxidase 4 (GPX4) was decreased by erastin or IKE." (PMID 36967385, 2023). "Importantly, combining systemic Ptgs2 loss does not promote additional benefits on Ptgs2-depleted tumor growth and mice survival, suggesting that tumor-derived PGE2 is sufficient to drive T cell-dependent immunosuppression and thereby cancer progression." (PMID 35945203, 2022). "It means that PACERR and PTGS2 may be more tumour‐specific therapeutic targets." (PMID 35184402, 2022).
tumor (continued). "Tumor cells treated with radiotherapy showed typical ferroptotic features, with mitochondrial atrophy and its increased membrane density, enhanced lipid peroxidation, as well as increased expression of the ferroptosis marker gene prostaglandin-endoperoxide synthase-2 (PTGS2)." (PMID 36505465, 2022). "The gene markers of M1 macrophages, such as PTGS2 and NOS2, had weak correlations with CD209 expression, whereas M2 macrophage markers had moderate and strong correlations, revealing the potential regulatory role of CD209 in tumor-associated macrophage (TAM) polarization." (PMID 35783255, 2022). "Activation of the PI3K/Akt signaling pathway can upregulate PTGS2, which has been proved to be involved in the production of inflammatory prostaglandins through stimulation events and in various biological processes such as tumor cell proliferation, angiogenesis, and invasion." (PMID 33688358, 2021). "Therefore, DAC-induced PTGS2 up-regulation could remove this limitation and counteract the anti-tumour effects of DAC." (PMID 33359448, 2021). "PC2 (driven by Ptgs2, Ptges, Inhba, Tacstd2, and Nfat5) could help distinguish between tumor and healthy, although in the Parsortix samples, healthy falls between the two tumor conditions on the PC1 axis." (PMID 35153760, 2021). "Inflammation is a key mediator of angiogenesis and lymph-angiogenesis with aberrant expression of PTGS2, and aberrant expression of PTGS2 was associated with tumor growth in the present study, but it has not been clearly elucidated and further functional biological experiments are required." (PMID 35096012, 2021). "gPTGS2 levels partially correlated with both tumor-associated and stroma-associated PTGS2 detected by IHC, indicating that gPTGS2 expression is not restricted to tumor cells as hypothesized before." (PMID 32168749, 2020). "Tumor-associated PTGS2 did not apparently affect patients’ overall survival, and the quantification of specific gPTGS2 levels in tissue lysates could not discriminate patient outcome." (PMID 32168749, 2020). "Thus, the contemporary presence of high or low PTGS2 levels in the tumor and stromal populations of the same sample was apparently infrequent in our cohort, suggesting the existence of distinct mechanisms of PTGS2 induction in the different cell populations of the same tumor." (PMID 32168749, 2020). "Moreover, our analysis also found a correlation between low PTGS2 expression and tumor recurrence." (PMID 29843383, 2018). "Tumor molecular profiles showed few associations with clinicopathological variables, and these included downregulation of PTGDR and PTGS1 in older patients, overexpression of PTGER2, and hypermethylation of PTGS2 in right side tumors as compared with left colon." (PMID 26207152, 2015). "Notably, expression of the tumour marker Ceacam6 and Cdcp1 were upregulated as was prostaglandin synthase 2 (Ptgs2) that might lead to a modified arachidonic acid metabolism pertinent to the respiratory epithelium." (PMID 21152443, 2010). "TN-induced PTGS2 downregulation leads to the inhibition of the JAK/STAT3/c-Myc signaling axis, resulting in suppression of tumor proliferation and the induction of autophagic cell death." (PMID 41800258, 2026). "PTGS2 (COX-2) is critically involved in CRC progression, while its inhibition suppresses tumor growth and enhances overall survival." (PMID 41154660, 2025). "Histopathological examination (HE) along with immunohistochemistry assays were conducted on isolated tumor tissues focusing on TYMS and PTGS2 expression." (PMID 39744483, 2025). "For example, in HCC cells and xenograft tumor models in nude mice, curcumin significantly downregulates the expression of SLC7A11, GPX4, GSS, and FTH1, while upregulating ACSL4 and PTGS2, thereby altering the ferroptosis-sensitive phenotype." (PMID 41515171, 2025). "Sh‐YTHDF2 and DNase I inhibited GPX4, SLC7A11, and FTH1 expression in the tumour, while increasing ACSL4 and PTGS2 levels and had a superimposed effect." (PMID 39865544, 2025).
tumor (continued). "This activation upregulates Ptgs1 and Ptgs2, the rate-limiting enzymes for prostaglandin synthesis, thereby increasing PGE2 production and suppressing anti-tumor immunity." (PMID 41383622, 2025). "Immune and Inflammatory Modulation: IFNGR1 and PTGS2 (COX-2) play roles in immune responses and inflammation, which can contribute to a tumor-supportive microenvironment." (PMID 41303451, 2025). "Genes Ptgs2, Cxcl1, Vegfa, Cxcl2, Col1a1 and Col1a2 were downregulated in cluster 0 of the A101 CAR-T-treated tumor compared to the mock-T-treated group which are involved in angiogenesis and tumor-promoting inflammation as well as EMT and tumor progression." (PMID 40568084, 2025). "The immune genes CXCL1, CXCL2, IL1B, IL6, CXCL8, PTGS2, and SPP1 demonstrated elevated expression levels in tumor tissue (TU) relative to all other tissues, thus validating the results obtained from the NanoString analysis (Supplementary 1)." (PMID 38979413, 2024). "Compared to the normal tissue in the TCGA cohort, ACOX2 (P < 0.001), PTGS1 (P < 0.001), PTGS2 (P < 0.001), and PPARGC1A (P < 0.001) were downregulated, while HAO1 (P < 0.001) was upregulated in tumor samples." (PMID 38706909, 2024). "CXCR1 and PTGS2 genes had significantly higher expression in patients with N1 metastasis, whereas VEGFB expression was significantly higher in tumour samples with N3 metastasis." (PMID 38426619, 2024). "Based on the results obtained, PTGS2, VEGFA, KDR, CXCR1 and CXCR2 were found to be significantly overexpressed in tumour samples compared to paired normal samples." (PMID 38426619, 2024). "The gene with the highest expression in SiHa is PTGS2, which codes for the cyclooxygenase-2 protein (COX-2) involved in tumor progression." (PMID 39409923, 2024). "The network of PTGS2 and PTGES2 with tumor suppressor genes showed nearly 70% physical interactions with 21 secondary nodes between these genes." (PMID 38201650, 2024). "Significant upregulation of PTGS2, VEGFA, KDR, CXCR1, and CXCR2 expression were observed in tumour samples compared with paired normal samples." (PMID 38426619, 2024). "Ptgs2 is an inducible gene and was shown at its primary characterization to be induced by the mitogen Rous Sarcoma Virus with its product, PGE2, mediating tumour cell proliferation." (PMID 40171466, 2024). "In this study, a significant increase in PTGS2 with VEGFA, KDR, CXCR1 and CXCR2 expression was observed in tumour samples compared to their paired normal samples, with the exception of VEGFB, whose expression was not statistically significant." (PMID 38426619, 2024). "Analysis from the acquired immunofluorescence pictures revealed that PTGS2, MMP9, MMP2, and CXCR 4 were mostly located around the nucleus in tumor tissues, and PPARG was mostly located inside the nucleus in tumor tissues." (PMID 38457601, 2024). "The functional assessment of MDSCs through the analysis of PTGS2, S100A8, IL10, TGFB1, and VEGFA expression provides a comprehensive view of their immunomodulatory activities within the tumor microenvironment." (PMID 39916959, 2024). "This study highlights the significance of PTGS2 and VEGF signalling genes in locally advanced OSCC by identifying their significant overexpression in tumour tissues." (PMID 38426619, 2024). "In our study, we found that PTGS2 and VEGF signalling pathway genes (VEGFA, VEGFB, KDR, CXCR1 and CXCR2) were upregulated in OSCC tumour tissues compared to their paired normal tissues." (PMID 38426619, 2024). "Cumulatively, a substantial reduction of GSH levels accompanied by the elevation of ROS, PTGS2 and LPO levels were detected in tumor tissues following Gi-F-CAA treatment compared with that in PBS, Gi-F and Gi-F-SA treatment group." (PMID 38212623, 2024). "Meanwhile, multiple oncoproteins and tumor suppressors promote this phenomenon and iron death proteins such as GPX4, ACSL4 and PTGS2 can be utilized in anti-tumor." (PMID 37542283, 2023).
tumor (continued). "The expression of PTGS2 and PTGES in orthotopic tumor tissues were notably higher in shNC than in shFADS1 mice, but they were not statistically different in the two groups with the deletion of gut microbes." (PMID 37041160, 2023). "TIMER analysis showed that DNAJB1, COL10A1, PTGS2, AFP, and EGF were correlated with tumor-infiltrating lymphocytes." (PMID 36967783, 2023). "Many of the DEGs were involved in ferroptosis (Ptgs2), enhanced T-cell function (Lef1), regulators of EMT (Zeb1, Zeb2, Vimentin, and Sfrp2), and fibrosis (Col1α1 and Acta2) in the tumor microenvironment." (PMID 36835036, 2023). "In non-tumor cells (HaCaT), the effect was inverse, with an upregulation of PTGS2 and its receptors (PTGER2, PTGER3, and PTGR4), indicating the pro-inflammatory effect of piperine on non-tumor cells." (PMID 36678600, 2023). "We first examined the expression of PTGS2 and CTLA4 in normal and tumor tissue samples for diverse types of cancer, employing the TNMplot tool of the KMplotter web platform." (PMID 38201508, 2023). "Elevated IFN sensitivity and inflammatory pathways were identified in EphA2KO tumours as the basis for the enhanced immune reaction, while they had decreased activity of TGF/SMAD signalling and the downstream effector Ptgs2/cyclooxygenase-2 (COX-2)." (PMID 36830852, 2023). "Compared to that in peritumor tissues, the expression of ferroptosis-inducing genes, including PTGS2, ALOX12, TFR2, and HMOX1, was decreased in tumor tissues, whereas ferroptosis-suppressor genes, including SLC7A11 and GPX4, were increased." (PMID 37554285, 2023). "The level of PTGS2, a ferroptosis marker, increased by approximately 40-fold in 5637 tumor tissues, while only increasing by about 2-fold in corresponding UMUC3 tumor tissues." (PMID 38062004, 2023). "The results demonstrate that the expression of EGFR, IGF1, PTGS2, FGF1, CAV1, and PLCB1 were significantly different (p < 0.01) in PABC tissues as compared to non-tumor tissues, with a similar pattern to that observed in the microarray analysis." (PMID 36035177, 2022). "Here, we discovered a novel mechanism of epigenetic modulation, that results in polarization of TAMs towards pro‐tumour M2 phenotype: CTCF binds to the overlapped promoter region of PACERR and PTGS2, leading to the transcription of PACERR." (PMID 35184402, 2022). "PTGS2 was the only gene differentially expressed (Log2FC = 1.88, p-value < 0.001, FDR = 0.011) in tumour samples from patients with high RDW (>1.03) versus low RDW." (PMID 36077723, 2022). "We first investigated the upregulated four genes (BDNF, PTGS2, CTNNB1, and GSK3B) in the tumor sample expression profile in CC patient tissue using RNAseq data." (PMID 35054980, 2022). "Four genes (BDNF, PTGS2, GSK3B, and CTNNB1) were significantly upregulated and one gene (HPGD) was significantly downregulated in primary tumor tissues compared with adjacent normal tissues throughout all the five in silico datasets." (PMID 35054980, 2022). "The expression of PTGS2, a marker of ferroptosis, was enhanced upon RSL3 treatment and further enhanced after ICG001 cotreatment, according to isolated tumor-related IF staining results." (PMID 36429010, 2022). "Our analysis using the HNSC dataset in the TCGA database revealed that the expression of PTGS2, MMP1, and MMP3 in tumor tissues was significantly higher." (PMID 36555343, 2022). "The analysis revealed that the relative expressions of PTGS2 and DNM1L were remarkably upregulated in HCC tumor tissues (n = 240) compared with normal samples (n = 193)." (PMID 35159089, 2022).